CHIA (chitinase acidic)
Description:
Degrades chitin and chitotriose. May participate in the defense against nematodes, fungi and other pathogens. Plays a role in T-helper cell type 2 (Th2) immune response. Contributes to the response to IL-13 and inflammation in response to IL-13. Stimulates chemokine production by pulmonary epithelial cells. Protects lung epithelial cells against apoptosis and promotes phosphorylation of AKT1. Its function in the inflammatory response and in protecting cells against apoptosis is inhibited by allosamidin, suggesting that the function of this protein depends on carbohydrate binding.
Synonyms: AMCase; TSA1902; CHIT2
Tractability: Small molecule: a structure with a bound ligand is known; a high-quality ligand is known; it has a high-quality binding pocket; it belongs to a druggable protein family. Antibody: its Gene Ontology location is reachable by antibodies, with high confidence; UniProt places it where antibodies can reach, with medium confidence; UniProt predicts a signal peptide or a membrane-spanning region. PROTAC: a small molecule that binds it is known.
Target class: Enzyme; Hydrolase
Safety:
Unwanted effects reported when the protein is acted on. In parentheses: how it was acted on, where the effect was seen, and who reports it.
asthma (source: ClinPGx)
Gene: Protein-coding gene on chromosome 1 (111,290,851 to 111,320,566, forward strand). Ensembl gene ENSG00000134216.
Subcellular location: Secreted (Isoform 1); Cytoplasm (Isoform 2); Cytoplasm (Isoform 3)
Pathways (Reactome):
Digestion and absorption: Digestion of dietary carbohydrate
Gene Ontology:
Molecular function: chitinase activity; kinase binding; protein binding; chitin binding; endochitinase activity; hydrolase activity, hydrolyzing O-glycosyl compounds
Biological process: chitin catabolic process; positive regulation of chemokine production; production of molecular mediator involved in inflammatory response; chitin metabolic process; polysaccharide digestion; carbohydrate metabolic process
Cellular component: extracellular region; cytoplasm
Genetic constraint (gnomAD): Loss-of-function variants: 47 observed, 56.37 expected, observed/expected ratio (o/e) 0.83, 90% interval 0.66 to 1.06. The upper end of that interval is the gene's LOEUF score, 1.06, which puts it in group 4 of 6, group 1 being the genes least tolerant of losing a copy. Missense variants: 648 observed, 617.37 expected, observed/expected ratio (o/e) 1.05, 90% interval 0.98 to 1.12. Synonymous variants: 268 observed, 231.32 expected, observed/expected ratio (o/e) 1.16, 90% interval 1.05 to 1.28.
Homologues: Orthologues: chimpanzee CHIA (95% identical), dog CHIA (89% identical), macaque CHIA (88% identical), pig CHIA (85% identical), rat Chia (82% identical), mouse Chia1 (81% identical), tropical clawed frog usp49 (80% identical), mouse Chil5 (61% identical), rat Chi3l3 (58% identical), mouse Chil3 (57% identical), mouse Chil4 (56% identical), mouse Chil6 (55% identical), and 37 more. Paralogues in human: CHIT1 (51% identical), OVGP1 (43% identical), CHI3L1 (41% identical), CHI3L2 (40% identical), CTBS (18% identical), CHID1 (16% identical).